ZNF202 (zinc finger protein 202)
Description:
Transcriptional repressor that binds to elements found predominantly in genes that participate in lipid metabolism. Among its targets are structural components of lipoprotein particles (apolipoproteins AIV, CIII, and E), enzymes involved in lipid processing (lipoprotein lipase, lecithin cholesteryl ester transferase), transporters involved in lipid homeostasis (ABCA1, ABCG1), and several genes involved in processes related to energy metabolism and vascular disease.
Synonyms: ZKSCAN10; ZSCAN42
Tractability: PROTAC: UniProt records ubiquitination sites on it; ubiquitination databases record sites on it.
Gene: Protein-coding gene on chromosome 11 (123,723,914 to 123,742,513, reverse strand). Ensembl gene ENSG00000166261.
Subcellular location: Nucleus
Subcellular location (Human Protein Atlas): Mitotic chromosome; Nucleoli rim; Nuclear bodies
Pathways (Reactome):
Gene expression (Transcription): Generic Transcription Pathway
Gene Ontology:
Molecular function: DNA-binding transcription repressor activity, RNA polymerase II-specific; protein binding; RNA polymerase II cis-regulatory region sequence-specific DNA binding; DNA-binding transcription factor activity, RNA polymerase II-specific; DNA-binding transcription factor activity; sequence-specific double-stranded DNA binding
Biological process: negative regulation of transcription by RNA polymerase II; lipid metabolic process; regulation of transcription by RNA polymerase II; negative regulation of DNA-templated transcription; regulation of DNA-templated transcription
Cellular component: nucleus
Genetic constraint (gnomAD): Loss-of-function variants: 26 observed, 58.56 expected, observed/expected ratio (o/e) 0.44, 90% interval 0.32 to 0.62. The upper end of that interval is the gene's LOEUF score, 0.62, which puts it in group 2 of 6, group 1 being the genes least tolerant of losing a copy. Missense variants: 625 observed, 812.31 expected, observed/expected ratio (o/e) 0.77, 90% interval 0.72 to 0.82. Synonymous variants: 286 observed, 307.62 expected, observed/expected ratio (o/e) 0.93, 90% interval 0.84 to 1.02.
Homologues: Orthologues: chimpanzee ZNF202 (99% identical), macaque ZNF202 (98% identical), dog ZNF202 (90% identical), rabbit ZNF202 (89% identical), guinea pig ZNF202 (86% identical), rat Zfp202 (79% identical), mouse Zfp202 (79% identical), pig ZNF202 (68% identical), Drosophila melanogaster CG12391 (12% identical), Drosophila melanogaster hb (10% identical), zebrafish plagl2 (10% identical), zebrafish ovol1b (8% identical), and 5 more. Paralogues in human: ZSCAN29 (29% identical), ZNF18 (26% identical), ZKSCAN2 (24% identical), ZNF496 (24% identical), ZNF446 (24% identical), ZSCAN32 (22% identical), ZNF274 (22% identical), ZNF444 (19% identical), ZSCAN18 (19% identical), ZNF174 (19% identical), ZSCAN5A (18% identical), ZSCAN5B (18% identical), and 17 more.
Diseases named in the same sentence as ZNF202 in open-access papers:
ZNF202 is named in the same sentence as 11 diseases in open-access papers, as found by Europe PMC text mining. Sharing a sentence is not in itself a finding about the gene and the disease. The quoted sentences say what the papers report.
dyslipidemia (2 papers, 2013 to 2023). "This discrepancy might be caused by changes in lipid driven transcriptional factors like Ppar, Lxr, and Fxr in response to Znf202 induced dyslipidemia." (PMID 23469003, 2013). "Also, it has been investigated that zinc cooperates in lipoprotein lipase and lecithin cholesteryl ester transferase pathways; thus, it is proposed that ZNF202 may be a probable gene vulnerable to developing dyslipidemia in human body." (PMID 37604307, 2023).
coronary heart disease (1 paper, 2013). "However, a sequence variation in the promoter of Znf202 did predict atherosclerosis and Ischemic Heart Disease." (PMID 23469003, 2013). "Whether or not Znf202 is the responsible gene within the identified chromosomal region that has been linked to hypoalphalipoproteinemia in the study with Utah pedigrees and has a direct or indirect association with the increased risk of coronary heart disease requires further investigation." (PMID 23469003, 2013).
hepatoma (1 paper, 2013). "To confirm the repressive effect of our Znf202 constructs, we overexpressed murine Znf202 in a mouse hepatoma cell line and showed reduction of expression of the majority of genes within both apolipoprotein gene clusters." (PMID 23469003, 2013). "Znf202 overexpression in mouse hepatoma cells mhAT3F2 resulted in downregulation of members of the Apoe/c1/c2 and Apoa1/c3/a4 gene cluster." (PMID 23469003, 2013). "This is corroborated by in vitro findings showing repressional activity of Znf202 on a range of target genes involved in lipid metabolism including ATP-binding cassette (ABC) transporters Abca1, Abcg1 and apolipoproteins Apoe and Apoa4, in hepatoma cells as well as monocytes." (PMID 23469003, 2013).
hypoalphalipoproteinemia (1 paper, 2013). A metabolic disorder characterized by deficiency of high density (alpha) lipoprotein in the blood. "In conclusion, we are the first to deliver in vivo proof for a functional role of Znf202 in lipid homeostasis and that znf202 overexpression causes hypoalphalipoproteinemia both in normolipidemic and hyperlipidemic mouse models." (PMID 23469003, 2013). "The zinc finger protein 202 (Znf202) gene has been identified in the chromosomal region 11q23 that is linked to heritable hypoalphalipoproteinemia in Utah pedigrees and distinct from an apolipoprotein gene cluster ApoAI/CIII/AIV/AV." (PMID 23469003, 2013). "The zinc finger protein Znf202 is a transcriptional suppressor of lipid related genes and has been linked to hypoalphalipoproteinemia." (PMID 23469003, 2013). "Although these in vivo data clearly link znf202 activity to hypoalphalipoproteinemia, the apparent lack of correlation between the in vitro data of us and others and the hepatic gene expression profiles at 5 days after adenoviral Znf202 administration was a surprise." (PMID 23469003, 2013).
melanoma (1 paper, 2006). A malignant, usually aggressive tumor composed of atypical, neoplastic melanocytes. "The same results indicate the gene ZNF202 is related to melanoma and cancers affecting the breast, cervix, ovary and lung." (PMID 17090329, 2006).
nasopharyngitis (1 paper, 2024). An inflammatory process that affects the nasopharynx. "Higher protein levels of ZNF202 were also detected in NPC tissues compared to nasopharyngitis tissues." (PMID 38287022, 2024).
cancer (2 papers, 2006 to 2014). A tumor composed of atypical neoplastic, often pleomorphic cells that invade other tissues. "Moreover, the expression level of AMACR in common carcinomas is known to be mostly regulated by various transcriptional factors, such as C/EBP family members, Sp1, and ZNF202." (PMID 25473890, 2014).
infection (1 paper, 2013). The state of being infected such as from the introduction of a foreign agent such as serum, vaccine, antigenic substance or organism. "Together with the altered hepatic gene expression pattern, hepatic Znf202 overexpression had an effect on lipid metabolism already at 24 h post infection." (PMID 23469003, 2013).
tumor (1 paper, 2024). "Next the relationship of ZNF202 and CYLD was analyzed by IHC in NPC tissues and a tumor tissue microarray." (PMID 38287022, 2024).
ZNF202 also shares sentences with these, for which no sentence is quoted: atherosclerosis (4 papers); prostate carcinoma (1).